IFNG (interferon gamma)
Diseases named in the same sentence as IFNG in open-access papers (continued):
Sharing a sentence is not in itself a finding about the gene and the disease.
colitis (continued). "Importantly, decreased IL-18, and to a lesser extent IFNγ, production was evident in Casp11−/− mice at 2 weeks, which may be ultimately responsible for defective IL-22 production observed in these mice during both experimental colitis and CAC." (PMID 30538296, 2019). "In contrast, when IL17A and IL17F were neutralized in the presence of IFNγ-producing cells minimal effect on weight loss or histopathological scores was observed indicating that inhibition of Th17 cytokine per se is not sufficient for the protection of colitis induction (data not shown)." (PMID 29416538, 2018). "This disruption of IFNγ signaling, was sufficient to inhibit the production of TH1 cytokines and improve 2, 4, 6-trinitrobenzene sulfonic acid induced colitis." (PMID 30429852, 2018). "As expected, DSS colitis significantly increased the expression of mature miR-146a, MCP-1, S100A8 and IFNγ." (PMID 30478292, 2018). "Our results showed that GABA administration reduced colon levels of inflammatory cytokines such as TNF-α, IFNγ, and IL-12 in DSS-induced colitis mice, while significantly increasing tissue levels of IL-10." (PMID 29867964, 2018). "Given the importance for IFNγ and ILC3 in innate immune cell-mediated acute intestinal inflammation, we next assessed their role in the CD4 T cell transfer model of colitis." (PMID 29416538, 2018). "Colitis development was dependent on IL23 induced IL17 and IFNγ production by ILC3 that accumulated in the gut in response to IL1β." (PMID 29081776, 2017). "Compared with the control, the serum levels of IL-1β, IL-6, IL-10, IFNγ, and TNFα were increased in DSS colitis mice." (PMID 27177331, 2016). "The rSjcystatin application after colitis decreased the proportion of Th1 subsets in these organs, due to the data of the percentage of CD4+IFNγ+ and relative expression of IFNγ mRNA descended in the spleen and MLN." (PMID 26728323, 2016). "In consequence, the inhibitory effect exerted by these compounds on the expression of IFNγ and IL-6 can also contribute to the improvement of the intestinal permeability observed in DSS experimental colitis." (PMID 27070642, 2016). "Administration of L. plantarum and L. brevis reduced IL1β, TNFα, and IFNγ, as well as the protein expressions of IL1β and IL6, and the signs of colitis in DSS-induced colitic mice." (PMID 26347738, 2015). "The fact that the elevated inflammatory cytokine expression such as IFNγ and IL-17A in the colon and accumulation of CD4+ T cells in cLP were observed in LTAC mice raised the question of whether these T cells turned out to gain pathogenic characters that would contribute to onset of colitis." (PMID 26132627, 2015). "In trinitrobenzene sulfonic acid (TNBS)-induced colitis mouse models supplemented with AA, T cells increase interferon-gamma (IFN-γ) production in a COX-2-dependent manner, enhancing lymph node cell activation." (PMID 41210682, 2025). "In addition, I3C therapy significantly reduced the mRNA expression of proinflammatory cytokines IL‐1β, IFNγ, and TNFα in DSS‐induced colitis mice." (PMID 40410944, 2025). "Naïve CD4+ T cells previously stimulated in the presence or absence of IL-36γ, from wild type (WT) or IFNγ-/- mice were transferred to Rag-/- mice to induce colitis." (PMID 40642091, 2025). "These infiltrates are typically accompanied by increased levels of proinflammatory cytokines, including IL-6/17, interferon-gamma (IFN-γ), and tumor necrosis factor alpha (TNF-α), which are thought to mediate mucosal injury and contribute to the severity of colitis." (PMID 40726872, 2025). "We observed a modest increase in HMGB1 and increased CD8+IFNγ+ cells during the colitis inflammatory process (DSS and UC) and in the early period after AOM administration, whereas CD8+IFNγ+ cells decreased and CD8+PDL1+ cells increased during carcinogenesis progression." (PMID 38999957, 2024).
colitis (continued). "During the colitis phase, cells were harvested, cultured with phorbol 12-myristate 13-acetate and ionomycin, and subsequently stained for CD3/CD4, followed by fixation, intracellular staining for IL-17A and IFNγ, and analysis using flow cytometry (FCM)." (PMID 39596393, 2024). "In conjunction with an abundance of effector T cell responses, myeloid cells in ICI-colitis also display an inflammatory gene signature enriched in TNF-α- and IFNγ-inducible elements such as CXCL16, CXCL9 and CXCL10, which encode chemokines that attract CXCR6+ and CXCR3+ T cells, respectively." (PMID 39247203, 2024). "Cytokines are important mediators of inflammation and elevated levels of major proinflammatory cytokines such as tumor necrosis factor (TNF), interleukin (IL)-6, IL-1β, and interferon-gamma (IFN-γ) are observed in patients with ulcerative colitis and also in chemically induced colitis models." (PMID 38998493, 2024). "Importantly, the same group later demonstrated that the priming of murine MSCs with the IFNγ and poly(I:C) improved the therapeutic effect of MSC transplantation in mice with induced colitis." (PMID 39201612, 2024). "A prior study indicated that a cocktail of proinflammatory cytokines (GM-CSF, IFNγ, TNFɑ) boosts CCR3 expression in human peripheral blood neutrophils from healthy donors, and expression of these cytokines is highly induced during STm colitis and Ab pneumonia." (PMID 39193987, 2024). "Infection by the nematode, T. spiralis, for example, attenuates DNBS-induced colitis by downregulating Th1-type cytokines, while exposure to eggs of the trematode S. mansoni protects mice from TNBS-induced colitis by diminishing IFNγ levels and enhancing IL-4 production." (PMID 37189818, 2023). "Therapeutic targeting of IFNγ-producing lymphocytes or regulatory networks, may hold the key to reversing CPI-colitis." (PMID 37872166, 2023). "Without IFNγ, IL-23 and Red 40 did not induce progressive colitis development and prevented colonic epithelial cell death, showcasing perhaps a specialized relationship between IL-23, IL-17, IFNγ, and overall TH17 signaling in the development of IBD in mice." (PMID 38179052, 2023). "Previous reports found that during DSS induced colitis, mice with a mutation to constitutively activate TRPV1 showed a significant increase in CD4+ T cells producing IL-17A but not IFNγ." (PMID 38109366, 2023). "In mouse DSS colitis model, both expression and function of the KCa3.1 channel are upregulated in the CD4+ T lymphocytes in the mesenteric lymph node, which is a driving force of the enhanced production of inflammatory cytokines, such as IFNγ." (PMID 36459135, 2023). "The numbers of CD69−CD103− T cells and CD69+CD103+ CD4+ TRM cells expressing IFNγ or IL-17A were similar between mice with or without colitis." (PMID 35844584, 2022). "The previous study has demonstrated that IFNG plays key roles in the initiation of IBD, and the IFNG deficient mice did not develop DSS-induced colitis." (PMID 35462887, 2022). "Notably, the number of CD4+ T cells expressing IL-17A was significantly increased in mice with DSS-induced colitis, while numbers of CD4+ T cells expressing IFNγ remained unchanged." (PMID 35844584, 2022). "Surprisingly, CD69+CD103− CD4+ TRM cells were the major source of IL-17A and IFNγ in the gut of mice with or without DSS-induced colitis." (PMID 35844584, 2022). "Percentages of IL-17A– or IFNγ-expressing CD4+ T cells were increased, whereas percentages of IL-17A– or IFNγ-expressing CD8+ T cells were not changed in mice with colitis compared with control mice." (PMID 35844584, 2022). "IFNγ expression was not different in CD69+CD103− subset between mice with or without DSS-induced colitis." (PMID 35844584, 2022). "In contrast, the numbers as well as percentages of IFNγ or IL-17A–expressing CD8+ T cells were not changed in mice with colitis." (PMID 35844584, 2022).
colitis (continued). "As for colitis, it has been shown that TRM cells are increased in the gut of patients with IBD and have a pro-inflammatory phenotype that CD69+ T cells expressed higher levels of IFNγ, IL-13, IL-17A, and TNF mRNA than CD69− T cells." (PMID 35844584, 2022). "Hence, we sought to establish an overview of IFNγ-producing cLP cells in naïve mice and mice with DSS-elicited colitis." (PMID 34795671, 2021). "Of note, the T cell response to the colitis process was totally blunted in the treated group, an effect evidenced across different T cell subpopulations, such as cytotoxic CD8+ T cells, Th1 (CD4+IFNg+), Th2 (CD4+IL4+), Th17 (CD4+IL17+), and Tregs (CD4+FoxP3+)." (PMID 34072532, 2021). "In a murine model of dextran sodium sulfate induced colitis Pglyrp2 showed anti-inflammatory properties by promoting normal gut flora and preventing induction of interferon-gamma." (PMID 33833993, 2021). "Previous studies showed that γδ T cell depletion induces greater colonic damage, reduced KGF secretion, increased IFNγ production by αβ T cells and decreased IEC proliferation during DSS-induced colitis, suggesting that γδ IELs can promote mucosal repair following epithelial injury." (PMID 34312491, 2021). "IFNγ preconditioning has been widely studied and improved MSC efficacy in models where an immunomodulatory effect of MSC is expected, such as graft versus host disease, colitis, or sepsis." (PMID 33384991, 2020). "From a functional perspective, the adoptive transfer of these cells into a RagKO murine colitis model found that the Treg cells lost FOXP3 expression after 8 weeks, there was an accumulation of IFNγ-producing Th1 cells and thus, the development of colitis was not prevented." (PMID 33013855, 2020). "Surprisingly, we found that genetic ablation of IL-23 resulted in reduction of IFNγ-producing ILCs but not T cells during C. jejuni infection suggesting that ILCs can contribute to colitis development by IFNγ production during early stages of infection." (PMID 33488580, 2020). "Furthermore, cLP ILCs from T-betΔNCR+ILC DSS-colitis mice produced higher IL-13 and IL-5 after stimulation than ILCs from DSS-WT mice, whereas IL-17A and IFNγ production by ILCs were equivalent in both groups." (PMID 30356098, 2019). "IL10, which has been shown to downregulate IFNγ expression and to protect from colitis was not increased in Tbet knockout mice." (PMID 31572375, 2019). "Our results are in contrast with this model since in our hands CD4 T cell transfer colitis is induced even in the absence of IFNγ." (PMID 29416538, 2018). "Colitis induction in the absence of IFNγ-producing T cells is preferentially driven by Th17-related mediators including IL17A and IL17F." (PMID 29416538, 2018). "Collectively, our findings suggest that IFNγ contributes to colonic inflammation but its absence does not prevent T cell transfer colitis." (PMID 29416538, 2018). "Since CD4 T cell-induced colitis develops in the absence of IFNγ, we thus assessed the pro-inflammatory cytokine profile of colitogenic CD4 T cells in the presence or absence of IFNγ." (PMID 29416538, 2018). "As expected, colitis induced by CD4+CD45RBhigh T cells in immune-depleted mice was associated with a significant increase in Th17 genes, IFNG, IL10 as well as S100A8 and S100A9 (data not shown)." (PMID 30405600, 2018). "The differential mode of CD4 T cell priming may thus explain some of the observed discrepancies with regard to the role of IFNγ and/or IL17 in colitis induction." (PMID 29416538, 2018). "Oxazolone-induced colitis is mediated by IL-4 driven Th2 cells rather than IL-12/IFNγ-driven Th1 cells." (PMID 29168738, 2017). "Specifically, mice with proximally spread, but not distally contained, colitis have increased IL-1β, IL-6, IL-17, TNFα, and IFNγ combined with decreased IL-10 in the distal colon." (PMID 26121642, 2015).
colitis (continued). "Instead, the accumulation of IFNγ+, IL-6+ and IL-17A+ IEL cells in prolapsed CD4cre:PP4f/f mice may only occur during the latter phase of colitis pathogenesis." (PMID 24904742, 2014). "The cytokine profile and histopathology of murine DSS-colitis has similarities with both forms of IBD, namely elevation of pro-inflammatory cytokines, such as TNFα and IFNγ, transmural inflammation, and aphthous erosions (like CD) as well as increased levels of IL-4 and crypt abscesses (like UC)." (PMID 23468885, 2013). "Additionally, it is noteworthy that ATG7 is up‐regulated in A‐CD patients and experimental colitis mouse models, predominantly expressed in pro‐inflammatory CD4+IFNγ+ T cells, indicating that ATG7 affects the CD4+ T cells differentiation in the process of inflammation." (PMID 40887825, 2025). "Further, the IL-36/IFNγ pathway has not been assessed in the adoptive transfer model of colitis." (PMID 40642091, 2025). "The expression of AIF1 is induced by inflammatory cytokines, including interferon-gamma (IFN-γ), and contributes to the modulation of immune responses, particularly by influencing the function of T helper 1 (Th1) cells, as evidenced by studies in colitis mouse models." (PMID 40361384, 2025). "To determine whether IFNγ was functionally important in CPI colitis, we administered neutralising anti-IFNγ monoclonal antibodies, or isotype-matched control antibodies, to mice during induction of CPI colitis." (PMID 37872166, 2023). "Interestingly, the CRAC channel inhibitor BTP2 or CM4620 was shown to significantly reduce the production of inflammatory cytokines (such as IFNγ, TNF, IL-17A, IL-13, and IL-4) from human intestinal T cells, B cells, ILCs and myeloid cells, and improve colon inflammation in a mouse model of IBD." (PMID 36459135, 2023). "In the present study, 9 μM DCL inhibited LPS/IFNγ-induced activation of MAPKs in RAW264.7 cells, suggesting that the DCL-induced inhibition of MAPK activation may contribute to its anti-inflammatory and anti-colitis effects." (PMID 35321327, 2022). "Furthermore, IP administration reduced disease severity in the DSS colitis model, and this was accompanied by a decrease in the expression of pro-inflammatory cytokines IL-12, TNF, IFNγ, and IL-1β, and an increase in the expression of the anti-inflammatory cytokine IL-10." (PMID 35052669, 2022). "Furthermore, a trend towards decreased IFNγ expression was observed in the mLNs of Il36r−/− T cell recipient mice (p = 0.1), indicating that CD4+ T cell IL-36R signalling promotes the differentiation of Th1 responses during colitis." (PMID 35177818, 2022). "The IFNG-response pathway is up-regulated in both UC and DCC, but with an enhanced activation in both DCC and PDC indicating that targeting this pathway may be even more effective in ICI-colitis." (PMID 34147519, 2021). "However, in contrast to IFNγ and IL-17, abrogation of IL-22 signaling in mice with impaired IL-10 signaling did not have impact on C. jejuni-induced colitis and bacterial clearance." (PMID 34938670, 2021). "Soybean-derived dipeptides and tripeptides decreased the colonic expressions of proinflammatory IFNG, IL-1B, IL-12B, TNF, and IL-17A and MPO activity and increased Foxp3 expression and CD4+CD25+ T cells; therefore, the colon and ileum inflammation of piglets with DSS-induced colitis was attenuated." (PMID 32963495, 2020). "This may be because IL-12p70 is known to be dispensable for colitis, but IL-23 and IFNγ are not, suggesting that IFNγ production by CD4 T cells may result from IL-23 stimulation rather than IL-12 stimulation in this model." (PMID 32639988, 2020). "In line with this idea, using a T cell independent model of colitis, we showed that mice were fully protected from colitis in the absence of IFNγ (Rag1−/−Ifnγ−/− mice) or in the absence of ILC (anti-Thy1.2 depleted Rag1−/− mice or Rag2−/−RorcGFP/GFP mice), in agreement with previous studies." (PMID 29416538, 2018).
colitis (continued). "While we find that IFNγ drives acute intestinal inflammation in the anti-CD40 colitis model in an innate lymphoid cell (ILC)-dependent manner, IFNγ secreted by both transferred CD4 T cells and/or cells of the lymphopenic Rag1−/− recipient mice was dispensable for CD4 T cell-mediated colitis." (PMID 29416538, 2018). "Thus, we examined the expression of memory markers (CD44 and Eomes), NK cell receptors (NKG2D and Ly49a), cytolytic molecules (FasL and Perforin), and pro-inflammatory cytokines (IFNγ and TNFα) in MLN-derived NK1.1+CD8+ T cells from Yeti/CD1d KO mice during DSS-induced colitis." (PMID 30333822, 2018). "IFN-γ was shown to be significantly decreased in AOM/DSS mice models that lacked NLRP3 and caspase-1, suggesting that IFNγ could increase colon cell proliferation in primary grade DSS-induced colitis." (PMID 30447690, 2018). "The observation that both IFNγ and IL17 responses alone can induce colitis (in a T cell dependent model) raised the question of whether there is a “division of labor” between Th1 and Th17 responses in promoting intestinal inflammation or whether Th1 can regulate Th17 responses and vice versa." (PMID 29416538, 2018). "Interestingly, after SPX, the treatment with α7 agonist lost completely its protective effects against colitis, being unable to lower IL-1β concentrations and exacerbating TNBS-induced increase of IL-6 levels, while leaving unmodified IFNγ and IL-10 colonic content with respect to SPX/C mice." (PMID 29167641, 2017). "UCA reduced colonic levels of IFNγ in IL-10−/− mice but did not attenuate colitis." (PMID 21060867, 2010). "It is also possible that Plac8’s effect on CD4 T cell IFNγ production occurs transiently, and the magnitude of the enhancement of the IFNγ response in Plac8-/- T cells may not be large enough to manifest during a model of chronic inflammation such as this colitis model." (PMID 32639988, 2020). "The presence of IFNγ is a prerequisite in the anti-CD40 model of colitis whereas by using the T cell transfer model of colitis we clearly demonstrate that IFNγ is not necessary for the development of colitis as mice developed disease in the complete absence of IFNγ." (PMID 29416538, 2018). "Since CD4 T cell-mediated colitis develops in the absence of IFNγ production and in the absence of IFNγ the CD4 T cells preferentially differentiate into Th17-like cells, we next investigated whether neutralization of excessive IL17 responses in the absence of IFNγ attenuates colonic inflammation." (PMID 29416538, 2018). "We found significantly increased IL-17A+ CD4+ T cells, after DDC+DSS treatment while frequencies of Foxp3+ Treg, and IFNγ+ CD4+ T cells were comparable between DDC treated mice with and without acute DSS colitis." (PMID 38510236, 2024). "Despite Plac8’s regulation of IFNγ production by CD4 T cells in vitro, Plac8 ablation did not apparently alter T cell effector function in a T cell transfer model of colitis." (PMID 32639988, 2020). "While Plac8 significantly suppressed IFNγ production in IL-12 stimulated CD4 T cells in vitro, this phenotype was not captured in either a T cell transfer model of colitis or following Citrobacter rodentium infection." (PMID 32639988, 2020). "Our findings show that IFNγ antagonizes IL17 responses, and absence of IFNγ results in a predominant IL17-driven immune response that is sufficient to induce colitis." (PMID 29416538, 2018). "In a T cell transfer model of colitis, Tpl2 ablation within the transferred T cell population reduced the proportion of CD4 T cells expressing IFNγ without altering IL-17 expression." (PMID 25781948, 2015). "In a murine T cell transfer model of colitis, transfer of Tpl2−/− T cells resulted in reduced proportions of CD4 T cells expressing IFNγ, but not IL-17A, compared to that induced by wild type T cells." (PMID 25781948, 2015). "In addition, the expression of IFNγ and IDO was not altered in the colon upon colitis induction." (PMID 17375199, 2007).